MYC (MYC proto-oncogene, bHLH transcription factor)
Diseases named in the same sentence as MYC in open-access papers (continued):
Sharing a sentence is not in itself a finding about the gene and the disease.
lymphoma (continued). "There was also significant enrichment in disease gene sets (from DisGeNET33) related to leukaemia and lymphoma (P < 0.01), including proto-oncogenes such as BCL2 and MYC." (PMID 33637755, 2021). "In total, PLIER identified 137 rearrangements involving MYC, BCL2, and BCL6: 56 MYC rearrangements (in 49 lymphoma samples), 39 BCL2 rearrangements (in 34 samples), and 42 BCL6 rearrangements (in 40 samples)." (PMID 34099699, 2021). "In line with this, translocations in lymphomas and leukemias occur either in oncogenes active at some stages of B cell maturation (like BCL2, MYC) or in genes orchestrating B cell development and activation (e.g., CD79B, PAX5)." (PMID 34210001, 2021). "Inhibition of CDK9 by selective inhibitors (e.g., AZ5576) or by genetic knockdown negatively regulated MYC and MCL-1 expression, and induced apoptosis in primary and transformed cells from this lymphoma, providing an attractive therapeutic strategy." (PMID 34041038, 2021). "Here, we examine the effect of a synthetic eIF4A inhibitor (CR-1-31 B) against aggressive, MYC and BCL2 positive lymphomas and we specifically explore potential mechanisms of resistance to the eIF4A inhibitor treatment." (PMID 33562682, 2021). "Thus, mutants affecting MYC proteins may augment quantitative oncogenic effects on the expression of normal MYC-target genes with qualitative oncogenic effects, by which sets of cell cycle genes are abnormally targeted by MYC as B cells transition into lymphoma cells." (PMID 34885204, 2021). "Given the oncogenic role of MYC in lymphomagenesis and an established PRMT5/MYC axis in human cancer, we sought to validate the functionality of the PRMT5/MYC axis in canine lymphoma." (PMID 33989303, 2021). "BL need to be differentiated from high-grade B-cell lymphoma with MYC and BCL2 and/or BCL6 rearrangements, so called double-hit and triple-hit lymphomas." (PMID 34572754, 2021). "Using the Eμ-Myc lymphoma model, we showed that CXCR4 transcript and surface expression is enhanced by oncogenic MYC." (PMID 34363012, 2021). "Overexpressed MYC and BCL2 in double-hit lymphoma and double expressing lymphoma has poor prognosis." (PMID 34372899, 2021). "In contrast, 28% of the patients with DLBCL presented BCL6 rearrangement, 25% presented c-MYC rearrangement, and 16% presented BCL2 rearrangement, with 16% presenting double-hit lymphomas." (PMID 34819573, 2021). "Triple‐hit lymphoma (THL), which is classified into high‐grade B‐cell lymphoma with rearrangements of MYC, BCL2 and BCL6, presents aggressive biological behaviour." (PMID 34698437, 2021). "Twenty-eight percent of the patients with DLBCL presented BCL6 rearrangement, 25% presented c-MYC rearrangement, and 16% presented BCL2 rearrangement, with 16% presenting double-hit lymphomas." (PMID 34819573, 2021). "The second patient was a 60-year-old man with hepatic involvement and 60% to 70% MYC expression and 50% to 70% BCL-2 expression by IHC, consistent with a double-expressing lymphoma." (PMID 33311588, 2021). "Another important consideration is the presence of genetic rearrangements of the MYC, BCL2, and BCL6 genes that identifies patients with what is called double- or triple-hit lymphomas (MYC with BCL2 and/or BCL6 rearrangements)." (PMID 34945817, 2021). "Patients with ABC-DLBCL or genetic alterations in MYC and BCL2 and/or BCL6, called double hit (DHL) or triple hit lymphomas (THL), generally have a poor survival prognosis." (PMID 35008680, 2021). "Diffuse large B-cell lymphoma (DLBCL) with co-expression of MYC and BCL2 proteins is referred to as double expressor lymphoma." (PMID 34282799, 2021). "Patient 1 had a double-hit lymphoma with a MYC translocation and an additional BCL6 translocation and patient 5 had a triple hit lymphoma with additional BCL2 and BCL6 translocations." (PMID 33561953, 2021).
lymphoma (continued). "Li and colleagues tested BETi action on MYC activity and found that in both MYC/BCL2 DHL and MYC/BCL2/BCL6, triple-hit lymphoma cells were responsive to BETi (JQ1, I-BET, OTX) treatment." (PMID 33801599, 2021). "DNAi 1T, 3T, 4T, and 5T, having demonstrated downregulation of MYC promoter activity, were examined further for MYC G4-stabilization and intracellular activity in RAJI and CA46 lymphoma cell lines." (PMID 34577013, 2021). "The rest 13 patients all had MYC rearrangement, and among them 4 double-hit lymphomas (DHL) and 5 triple-hit lymphomas (THL) were identified." (PMID 33754004, 2021). "Notable genes with SNV-associated increased expression include TERT, COPS3, POLE2 and HDAC2—involving multiple cancer types—MYC, BCL2, PIM1 and IGLL5—involving lymphomas—and CYHR1—involving pediatric low-grade gliomas." (PMID 33554123, 2021). "Intriguingly, MYC and EZH2 create a positive loop that constantly leads to MYC and EZH2 overexpression, and both act together to silence tumor suppressor miRNAs in aggressive lymphoma cells, such as hsa-miR-150." (PMID 35008626, 2021). "“Double-hit” (with MYC, BCL2, or BCL6 alterations) and “triple-hit” (with MYC, BCL2, and BCL6 alterations) lymphomas are also aggressive in nature, and are part of the high-grade B-cell lymphomas." (PMID 34947882, 2021). "DLBCL, NOS “double expressor” seems to correlate with a worst prognosis, but the double expression of these two proteins is not necessarily a surrogate indicator of double translocation of c-MYC and BCL2 genes (“double-hit lymphomas”)." (PMID 34030716, 2021). "In the most recent WHO review of lymphoma classification, the DHL/THL category is now recognized as "high-grade B-cell lymphoma (HGBL) with rearrangements of MYC and Bcl-2 and/or Bcl-6." (PMID 33412518, 2021). "Immunophenotyping and molecular studies, performed later, established a diagnosis of de novo B-cell precursor leukemia/lymphoma with MYC, BCL2 rearrangements (Double-hit lymphoma)." (PMID 34307232, 2021). "The presence of rearrangements in all three of the genes (MYC, BCL2 and BCL6) characterizes a further subgroup of high-grade lymphomas called triple-hit lymphoma." (PMID 34943410, 2021). "Inactivation of MYC downregulated PD-L1 expression in melanoma, NSCLC, esophageal squamous cell carcinoma (ESCC), leukemia, lymphoma, and pancreatic cancer." (PMID 34088360, 2021). "Our study identifies a unique set of cases that have concurrent translocations and copy number gains in MYC, BCL2, and/or BCL6 outside of DH/TH lymphoma that cannot readily be identified using standard FISH alone." (PMID 33168821, 2020). "Oxidative stress, namely H2O2 has been demonstrated to promote lymphoma stemness phenotype, through the activation of the wingless (WNT)/β-catenin/MYC/sex determining region Y box 2 (SOX2) axis in the anaplastic lymphoma kinase-positive ALCL." (PMID 32197371, 2020). "While translocations in MYC, BCL2, and BCL6 represent significant genomic events in lymphoma, less is known about the contribution of chromosomal copy number alterations (CNAs) in these genes to existing translocations." (PMID 33168821, 2020). "Taken together, we show that targeting c-MYC and BCL2 expression into mouse GC B cells or pan-B cells generates a clinically relevant mouse model of double-expressor lymphoma." (PMID 32695674, 2020). "Gene sets or transcriptional pathways commonly regulated between H3.3K27M mouse HGG, H3.3K27M mouse lymphoma and human DIPG included RAS, PI3K/AKT signalling and MYC targets." (PMID 33277484, 2020). "Although IGH/MYC translocation in association with dysregulation of antiapoptotic pathway leads to worse prognosis in lymphomas, the novel agent-based regimen showed good efficacy, suggesting that IGH/MYC plays a different role in the pathogenesis of MM." (PMID 33381329, 2020). "Another significant outcome was that the Co-expression of c-MYC and BCL2 induced lymphoma was spontaneous and occured at an early age." (PMID 32695674, 2020).
lymphoma (continued). "We first demonstrated that SBP enzymes are overexpressed in BL, compared to another aggressive lymphoma, DLBCL, and transcriptionally controlled by MYC via ATF4." (PMID 32138178, 2020). "High-grade B-cell lymphomas with MYC and BCL2 and/or BCL6 rearrangements represent a quite recently defined entity of lymphoma with aggressive nature, high genomic complexity and poor prognosis." (PMID 33339535, 2020). "Loss of BCL-w sensitized B-cell to growth factor deprivation-induced B-cell apoptosis and suppressed MYC-induced lymphomagenesis, suggesting a crucial role of BCL-w in B-cell survival and lymphoma development." (PMID 32549409, 2020). "Taken together, these data indicated that K427 of MYC is critical for UBE3B-catalyzed MYC ubiquitination and the functions of TRIB3 in promoting lymphoma cell growth are dependent on T58 phosphorylation of MYC." (PMID 33298911, 2020). "Rare cases of follicular lymphoma transform to a high-grade B-cell lymphoma with MYC and BCL2 rearrangements or "double-hit lymphoma"." (PMID 32183313, 2020). "Double/triple hit lymphoma (DH/TH), known as high-grade B-cell lymphoma (HGBL), is an aggressive diffuse large B cell lymphoma (DLBCL), defined as having concurrent MYC, BCL2, and/or BCL6 gene rearrangements." (PMID 33168821, 2020). "In comparison, the reference HDAC inhibitor, SAHA, only marginally reduced the expression of the poor prognostic factors of MYC, BCL-2, and BCL-6 in the tested lymphoma cell lines." (PMID 32575557, 2020). "MYC target genes were among the most upregulated gene sets in H3.3K27M mouse HGG and lymphomas, and human DIPGs." (PMID 33277484, 2020). "The 2016 WHO classification recognizes and categorizes high‐grade B‐cell lymphomas (HGBCL) with MYC and BCL2 and/or BCL6 gene rearrangements as a separate entity, commonly referred to as “double‐hit” lymphomas." (PMID 31659781, 2020). "In this study, we found that lymphoma cells with high TRIB3 and MYC expression were more sensitive to PCM4 than those with low TRIB3 or MYC expression and that PCM4 increased the sensitivity of lymphoma cells to DOX due to decreased MYC expression." (PMID 33298911, 2020). "Specific oncogenes, such as MYC, BCL-2, and BCL-6, converge proliferation, differentiation, and anti-apoptotic signaling in lymphoma cells and play critical roles in lymphomas." (PMID 32296035, 2020). "Diffuse large B cell (DLBCL) and high grade B cell lymphomas (HGBL) demonstrating MYC translocation with concurrent BCL2 and/or BCL6 rearrangements, colloquially called double and triple hit lymphomas (DHL and THL), have poor clinical outcomes." (PMID 31932576, 2020). "Zhang and colleagues observed the epigenetic regulation of miR-29 by targeting HDAC3, MYC, and EZH2 in lymphomas." (PMID 32411322, 2020). "Other two subtypes represented by Double-Hit Lymphomas (DHL) (5–10% of all DLBCL lymphomas) and Double-Expressor Lymphomas (DEL), present MYC and BCL2 protein overexpression, together with the GCB and ABC subtypes." (PMID 33216822, 2020). "These malignancies are also known as double-hit (MYC/BCL2 or MYC/BCL6 translocations) and triple-hit (MYC/BCL2/BCL6 translocations) lymphomas (DHL/THL), and represent 5–10% of DLBCL patients." (PMID 33260693, 2020). "Mechanistically, this compound was described to downregulate MYC expression by promoting BRD2 and BRD4 displacement from MYC promoter region in both human lymphoma and T-ALL cell lines, as well as in mouse models of MM." (PMID 31581671, 2019). "Exemplarily, our analysis provided a close look on the transition range between FL and DLBCL, on DLBCL with poor prognosis showing expression patterns resembling that of BL, and particularly on ‘double-hit’ MYC and BCL2 transformed lymphomas." (PMID 31039827, 2019). "The G2/M checkpoint inhibitors are currently in clinical trials for treatment of various MYC-driven cancers, including lung cancer (NCT02688907), lymphoma, and ovarian cancer." (PMID 31848373, 2019).
lymphoma (continued). "In the most recent WHO revision of lymphoma classification, DHL/THL category is now recognized as "high-grade B cell lymphoma (HGBL) with rearrangements of MYC and BCL-2 and/or BCL-6." (PMID 31288832, 2019). "22.4% of patients (11/49) were positive for both c-MYC and BCL-2 proteins, and was considered as double-expression lymphoma (DEL)." (PMID 31702637, 2019). "For multivariate analysis, the parameters MYC, NCCN-IPI, necrosisPET and SUVmax single highest were used due to their prognostic impact on lymphoma-related deaths in univariate analysis." (PMID 31028445, 2019). "Loss of BCL-w sensitized B cell to growth factor deprivation-induced cell apoptosis and suppressed MYC-induced lymphomagenesis, suggesting a crucial role of BCL-w in B cell survival and lymphoma development." (PMID 30881917, 2019). "In the 2016 WHO classification, this category has been eliminated and replaced by the category “high-grade B cell lymphoma, with MYC and BCL-2 and/or BCL-6 rearrangements”, which encompasses “double” and “triple-hit” lymphomas." (PMID 31115699, 2019). "Although EZH2, MYC, BCL2 and BCL6 are important prognostic biomarkers for lymphomas, our study shows that they poorly influence the sensitivity of lymphoma cell lines to DZNep-mediated apoptosis." (PMID 31419226, 2019). "Among the 51 cases with MYC/BCL2 co-expression, 14 cases showed concurrence of MYC, BCL2 and/or BCL6 genetic abnormalities, and the remaining 37 cases were classified as double-expressor lymphoma (DEL)." (PMID 31315646, 2019). "Our analysis provided a novel look on the transition range between FL and DLBCL, on DLBCL with poor prognosis showing expression patterns resembling that of Burkitt’s lymphoma and particularly on ‘double-hit’ MYC and BCL2 transformed lymphomas." (PMID 31039827, 2019). "Earlier studies reported that 5–15% of DLBCL harbored MYC, BLC2, and/or BCL6 translocations and were called “double-hit” lymphoma (DHL) or triple-hit lymphoma (THL)." (PMID 31288832, 2019). "First, to better characterize the interaction of MYC with SPT5, we used reciprocal co-immunoprecipitation from HEK293, U2OS, and T-lymphoma cells to confirm interaction of endogenous MYC and SPT5." (PMID 30928206, 2019). "High-grade B-cell lymphoma, with MYC and BCL2 and/or BCL6 translocations (so called “double-hit” or “triple-hit” lymphomas in the WHO 2008) often show complex karyotypes." (PMID 30696948, 2019). "Our findings suggest that the high-grade lymphoma with MYC and BCL2 translocations evolved through transformation of the FL by a process that entailed acquisition of the MYC translocation." (PMID 29793519, 2018). "The CpG-STAT3dODN blocked STAT3 DNA binding and activity, thus reducing expression of downstream target genes, such as MYC and BCL2L1, in human and mouse lymphoma cells." (PMID 29433938, 2018). "Inhibition of FAO significantly delays constitutively active MYC-driven lymphoma development in a transgenic model, whereas increase in FAO facilitates the tricarboxylic acid (TCA) cycle and ATP production in MYC-overexpressing TNBC." (PMID 29907133, 2018). "Ours is the first reported case of composite lymphoma that includes elements of FL, CLL/SLL and high-grade B-cell lymphoma with MYC and BCL2 rearrangements." (PMID 29793519, 2018). "As a proof of concept that TAK-659 inhibits LMP2A/MYC lymphoma development and to corroborate our tumor cell transfer data, we treated a limited number of MYC (16- to 24-week-old) and LMP2A/MYC (6- to 10-week-old) transgenic mice before they developed tumors." (PMID 30135222, 2018). "DLBCLs that co-express high levels of MYC and BCL-2 proteins due to mechanisms other than chromosomal translocations are referred to as “dual expresser lymphomas” (DEL) and represent ~30% of DLBCL." (PMID 30671383, 2018).
lymphoma (continued). "DLBCL lymphomas that contain both rearrangements in BCL-2 and translocation of MYC are classified as “double hit lymphomas” (DHL) and represent ~10% of DLBCL cases." (PMID 30671383, 2018). "Because PLK1 has been implicated in molecular cross talk with MYC and volasertib possibly has an inhibitory activity on the BRD4 protein, it is plausible that therapeutic targeting of PLK1 in combination with JQ1 might yield a more favorable therapeutic index in MYC-associated lymphomas." (PMID 30323893, 2018). "A previous study showed that 2-dG impacted the cell viability of lymphoma cells as a single agent and reduced cell numbers synergistically with PI3K inhibitors and c-MYC antagonists." (PMID 29861847, 2018). "This agent extended survival when combined with chemotherapy in both the Eμ-MYC/eIF4E and Eμ-MYC/PTEN+/− lymphoma models, in which MYC and mTOR are deregulated to drive lymphoma onset." (PMID 29799508, 2018). "Further, signaling analysis via Western blot in the double-hit lymphoma cell line, KPUM-UH1, suggests that phospho-c-MYC is modified with 9-ING-41 treatment." (PMID 29383130, 2017). "MYCV394D is unable to repress wild-type MYC targets such as Cyclin Dependent Kinase Inhibitor 1A (CDKN1A/p21CIP) and Cyclin Dependent Kinase Inhibitor 2B (CDKN2B/p15INK4B), in a transgenic lymphoma model." (PMID 28505071, 2017). "c-MYC- and PI3K/mTOR-inhibitors decreased viability of the lymphoma cells and led to decreased glucose uptake, expression of glycolysis-associated genes, and glucose metabolism-regulating miRNAs." (PMID 28724379, 2017). "The combination of MYC translocation with translocations of BCL2 and BCL6 can also occur, defining the triple-hit lymphomas (THL)." (PMID 28061782, 2017). "In TSC2+/−Eμ-Myc lymphomas, DHX9 suppression resulted in elevated levels of p21, PUMA, BAX, NOXA, BIM, c-MYC, and PLK2." (PMID 28427210, 2017). "Here, we show that Chk1 is essential for normal B lymphopoiesis and that CHK1 expression levels affect transformation of lymphocytes induced by MYC overexpression or irradiation damage, in line with a core pro-survival role for CHK1 in murine lymphomas." (PMID 29167438, 2017). "These “double-hit” or “triple-hit” lymphomas are included in the updated WHO classification in the category of high-grade B‐cell lymphoma (HGBL), with rearrangements of MYC and BCL2 and/or BCL6." (PMID 29250206, 2017). "DA-EPOCH-R was previously suggested for patients with MYC and/or DH translocations based on preliminary data from a phase II study investigating DA-EPOCH-R in patients with MYC translocated aggressive lymphomas." (PMID 29088292, 2017). "These lymphomas belong to the new category called “High grade B cell lymphoma (HGBL), with rearrangements of MYC and BCL2 and/or BCL6”." (PMID 28375188, 2017). "AMPK functions in parallel with MYC and it is a therapeutic target in several hematopoietic malignancies including AML, ALL, CLL, lymphomas, and MM." (PMID 28674522, 2017). "A worse outcome than double-expressor lymphomas show high grade B‐cell lymphomas (HGBL) with rearrangements of MYC and BCL2 and/or BCL6, the so-called double-hit or triple-hit lymphomas, which constitute a single category in the updated WHO classification." (PMID 29250206, 2017). "Previous study has demonstrated that c-MYC inactivation up-regulated Bim through suppressing miR-17-92, a key post-transcriptional repressor of Bim in MYC-induced lymphomas model." (PMID 29156797, 2017). "The combination of BEZ235, along with vincristine treatment, enhanced apoptosis in Lck-Dlx5 lymphoma cells by downregulation of both AKT activity and MYC expression." (PMID 28362357, 2017). "The concurrent translocation of MYC and BCL2 occurs in approximately 5 % of DLBCLs and defines “double-hit” lymphomas that are treatment-refractory, with a median survival of ~8 months." (PMID 27580852, 2016).